H2AC4 (H2A clustered histone 4)
Description:
Core component of nucleosome. Nucleosomes wrap and compact DNA into chromatin, limiting DNA accessibility to the cellular machineries which require DNA as a template. Histones thereby play a central role in transcription regulation, DNA repair, DNA replication and chromosomal stability. DNA accessibility is regulated via a complex set of post-translational modifications of histones, also called histone code, and nucleosome remodeling.
Synonyms: H2AFM; HIST1H2AB; H2A/m
Gene: Protein-coding gene on chromosome 6 (26,033,092 to 26,033,618, reverse strand). Ensembl gene ENSG00000278463.
Subcellular location: Nucleus; Chromosome
Subcellular location (Human Protein Atlas): Nucleoplasm
Pathways (Reactome):
Gene expression (Transcription): B-WICH complex positively regulates rRNA expression; DNA methylation; ERCC6 (CSB) and EHMT2 (G9a) positively regulate rRNA expression; MLL4 and MLL3 complexes regulate expression of PPARG target genes in adipogenesis and hepatic steatosis; NoRC negatively regulates rRNA expression; PRC2 methylates histones and DNA; RNA Polymerase I Promoter Escape; RNA Polymerase I Promoter Opening; RUNX1 regulates genes involved in megakaryocyte differentiation and platelet function; RUNX1 regulates transcription of genes involved in differentiation of HSCs; Regulation of endogenous retroelements by KRAB-ZFP proteins; Regulation of endogenous retroelements by Piwi-interacting RNAs (piRNAs); Regulation of endogenous retroelements by the Human Silencing Hub (HUSH) complex; SIRT1 negatively regulates rRNA expression; Transcriptional regulation by small RNAs
Chromatin organization: CHD1 and CHD2 subfamily; CHD6, CHD7, CHD8, CHD9 subfamily; ChAHP complex assembly; HATs acetylate histones; HDACs deacetylate histones; Interaction of NuRD complexes with transcription factors; NuRD complex assembly; RMTs methylate histone arginines
Cell Cycle: Condensation of Prophase Chromosomes; Deposition of new CENPA-containing nucleosomes at the centromere; Inhibition of DNA recombination at telomere; Packaging Of Telomere Ends
DNA Repair: Cleavage of the damaged purine; Cleavage of the damaged pyrimidine; Recognition and association of DNA glycosylase with site containing an affected purine; Recognition and association of DNA glycosylase with site containing an affected pyrimidine
Disease: Defective pyroptosis; Dengue Virus-Host Interactions; HCMV Early Events; HCMV Late Events
Metabolism of proteins: Amyloid fiber formation; Metalloprotease DUBs; UCH proteinases; Ub-specific processing proteases
Signal Transduction: Activated PKN1 stimulates transcription of AR (androgen receptor) regulated genes KLK2 and KLK3
and 15 more pathways
Gene Ontology:
Molecular function: protein binding; structural constituent of chromatin; DNA binding; protein heterodimerization activity
Biological process: negative regulation of cell population proliferation; chromatin organization; heterochromatin formation; protein localization to CENP-A containing chromatin
Cellular component: CENP-A containing nucleosome; extracellular exosome; nucleoplasm; nucleosome; nucleus; chromosome
Genetic constraint (gnomAD): Loss-of-function variants: 8 observed, 6.76 expected, observed/expected ratio (o/e) 1.18, 90% interval 0.68 to 1.85. That is too few expected variants to judge how well the gene tolerates losing a copy. Missense variants: 260 observed, 196.36 expected, observed/expected ratio (o/e) 1.32, 90% interval 1.2 to 1.47. Synonymous variants: 129 observed, 83.78 expected, observed/expected ratio (o/e) 1.54, 90% interval 1.33 to 1.78.
Homologues: Orthologues: chimpanzee H2AC8 (100% identical), dog H2AC4 (100% identical), macaque H2AC8 (100% identical), mouse H2ac11 (100% identical), mouse H2ac13 (100% identical), rat hist1h2ail2 (100% identical), Drosophila melanogaster His2A:CG31618 (85% identical), Drosophila melanogaster His2A:CG33808 (85% identical), Drosophila melanogaster His2A:CG33814 (85% identical), Drosophila melanogaster His2A:CG33817 (85% identical), Drosophila melanogaster His2A:CG33820 (85% identical), Drosophila melanogaster His2A:CG33823 (85% identical), and 14 more. Paralogues in human: H2AC8 (100% identical), H2AC25 (99% identical), H2AC7 (99% identical), H2AC11 (98% identical), H2AC13 (98% identical), H2AC15 (98% identical), H2AC16 (98% identical), H2AC17 (98% identical), H2AC6 (98% identical), H2AC12 (97% identical), H2AC18 (97% identical), H2AC19 (97% identical), and 15 more.
Diseases named in the same sentence as H2AC4 in open-access papers:
H2AC4 is named in the same sentence as 2 diseases in open-access papers, as found by Europe PMC text mining. Sharing a sentence is not in itself a finding about the gene and the disease.
H2AC4 shares sentences with these, for which no sentence is quoted: benign breast tumors (1 paper); tumor (1).